LRG1 (leucine rich alpha-2-glycoprotein 1)
Diseases named in the same sentence as LRG1 in open-access papers (continued):
Sharing a sentence is not in itself a finding about the gene and the disease.
adenoma (4 papers, 2017 to 2021). A neoplasm arising from the epithelium. "Next to Hp, LAMP1, SYNE2, and ANXA6 were selected in the analysis for high‐risk adenomas, and also LRG1, RBP4, and FN1 for the high‐risk adenomas and CRCs." (PMID 31784980, 2020). "Two panels, one consisting of Hp and LRG1 and one of Hp, LRG1, RBP4, and FN1, were identified for high‐risk adenomas and CRCs detection (sensitivity of 66% and 62%, respectively, at specificity of 95%)." (PMID 31784980, 2020). "We identified a biomarker panel of Hp, LAMP1, SYNE2, and ANXA6 for identification of high‐risk adenomas and two biomarker panels – Hp and LRG1, as well as Hp, LRG1, RBP4, and FN1 – for identification of high‐risk adenomas and CRCs that outperformed hemoglobin." (PMID 31784980, 2020). "Synthetic peptides were selectively bound to the leucine-rich α-2-glycoprotein 1 (LRG1) that was overexpressed in CRC patients, and the level of plasma LRG1 was related to the progression of CRC from the adenoma stage to carcinoma." (PMID 32295170, 2020). "We conclude that Hp, LAMP1, SYNE2, LRG1, RBP4, FN1, and ANXA6 may be of value as stool biomarkers for early detection of high‐risk adenomas and CRCs." (PMID 31784980, 2020). "In this study, we demonstrated that the plasma level of LRG1 was increased in adenomas (LGN) and CRCs, and the concentration of LRG1 was remarkably increased in human CRCs compared with adenomas and controls, which was consistent with data found in the literature." (PMID 28376129, 2017). "The electrochemical biosensor detected the LRG1 protein in plasma samples of patients with CRC, thus showing its ability to diagnose the adenoma–carcinoma transition in gross human plasma samples." (PMID 32295170, 2020).
age-related macular degeneration (4 papers, 2021 to 2025). Age-related loss of vision in the central portion of the retina (macula), secondary to retinal degeneration. "Leucine-rich a-2-glycoprotein 1 (LRG1) is a candidate therapeutic target for treating the neovascular form of age-related macular degeneration (nvAMD)." (PMID 34445590, 2021). "One of the most compelling examples of LRG1 function in promoting diseased vessels is commonly described as the “TGF-β angiogenic switch”, which switches TGF-β signaling to a proliferative pathway in a variety of pathological settings, including age-related macular degeneration and cancer." (PMID 40769983, 2025).
Arthritis (4 papers, 2017 to 2025). Inflammation of a joint. "Leucine-rich alpha-2-glycoprotein 1 (LRG1) was previously reported to regulate inflammation and arthritis progression." (PMID 40665055, 2025).
cognitive deficits (4 papers, 2022 to 2025). "In contrast, both overexpressing DNMT3a or knockdown LRG1 in hippocampus can attenuate the synaptic disorders and rescue postoperative cognitive deficits in aged mice." (PMID 39722450, 2024). "Of note, the induction of cognitive impairment in mice by exposure to sevoflurane was shown to correlate with Lrg1 expression in the hippocampus." (PMID 35062948, 2022). "Notably, overexpression of Lrg1 in the hippocampus results in reduced synaptic vesicle density, contributing to cognitive impairment." (PMID 40904186, 2025). "This loss of DNMT3a function resulted in the derepression of leucine-rich alpha-2-glycoprotein 1 (LRG1), which activated TGF-β signaling and contributed to synaptic dysfunction and cognitive deficits." (PMID 40914484, 2025).
Hydrocephalus (4 papers, 2010 to 2021). Hydrocephalus is an active distension of the ventricular system of the brain resulting from inadequate passage of CSF from its point of production within the cerebral ventricles to its point of absorption into the systemic circulation. "Proteomic research using 2 D SDS-PAGE to analyze body fluids found LRG1 to be upregulated in cerebrospinal fluid and serum of patients with hydrocephalus and silicosis." (PMID 20831812, 2010).
Hypertension (4 papers, 2015 to 2024). The presence of chronic increased pressure in the systemic arterial system. "There is convincing evidence that a decreased expression of LRG1 is associated with increased fibrosis, aberrant vascular properties, and altered cardiomyocytes characteristics in ageing heart, and in failing heart induced by genetic modification, pressure overload, or hypertension." (PMID 28509980, 2015). "For hypertension, only one study discloses that serum LRG1 ranges from 11.3 to 28.1 μg/ml in patients with asymptomatic hypertension with high B-type natriuretic peptide, and it ranges from 9.5 to 17.0 μg/ml in those with low B-type natriuretic peptide." (PMID 38742172, 2024). "Alternatively, when hypertension was included as an independent variable in the models and systolic BP and ARB/ACEi use were excluded, LRG1 level was still associated with urinary albumin excretion." (PMID 37916147, 2023). "The level of LRG1 in hypertension/hyperlipidemia is rarely reported." (PMID 38742172, 2024). "LRG1 overexpression at the right dosage and right timing might prevent or reverse hypertension and hypertension-induced cardiomyopathy." (PMID 28509980, 2015). "In addition to periostin, literature retrieval and PCR verification were performed for other proteins that might be related to hypertension, such as Ahsg, Cst3, and Lrg1." (PMID 34084130, 2021). "However, it is not clear whether hypertension has a direct impact on the expression of Lrg1 or mediates LRG1 expression indirectly via hypertension-induced compensation." (PMID 28509980, 2015).
ischemia (4 papers, 2020 to 2024). A hypoperfusion of the BLOOD through an organ or tissue caused by a PATHOLOGIC CONSTRICTION or obstruction of its BLOOD VESSELS, or an absence of BLOOD CIRCULATION. "Many of them have been previously correlated with response to ischemia (MAP 4, HPX, S100A proteins) as well as with angiogenic- and revascularization-related processes (LCN2, LRG1, CD44, MAPKAPK2)." (PMID 32143690, 2020).
lupus nephritis (4 papers, 2020 to 2024). Glomerulonephritis in the context of systemic lupus erythematosus. "A recent study demonstrated that high levels of LRG1 in the plasma of patients affected by lupus nephritis correlate with poor renal function." (PMID 35062948, 2022). "We aimed to explore the expression and role of LRG1 in lupus nephritis (LN)." (PMID 32252660, 2020). "As hyperplasia of renal endothelial cells represents one of the most crucial pathological changes occurring in lupus nephritis, it is tempting to speculate that LRG1-driven aberrant angiogenesis might represent a contributing factor, although further studies are needed to confirm this hypothesis." (PMID 35062948, 2022).
neuroblastoma (4 papers, 2013 to 2022). Neuroblastoma (NB) is the most common solid, extracranial childhood tumor. "In addition, MIR335 inhibits the mRNA transcribed by LRG1 gene reducing the migration of neuroblastoma cells." (PMID 32582296, 2020).
psoriasis (4 papers, 2023 to 2025). An autoimmune condition characterized by red, well-delineated plaques with silvery scales that are usually on the extensor surfaces and scalp. "At present, it has been reported that LRG1 might be a useful biomarker to detect the occurrence of psoriasis in adults 23-25." (PMID 38250043, 2024). "However, the role of LRG1 in psoriasis remains largely unexplored." (PMID 38250043, 2024).
tuberculosis (4 papers, 2020 to 2024). A chronic, recurrent infection caused by the bacterium Mycobacterium tuberculosis. "In this study, 101 DE genes were identified and the most informative marker LRG1 has been previously identified as a potential biomarker for different infections (e.g., active tuberculosis) in humans." (PMID 36579334, 2022). "LRG1 serum levels in tuberculosis patients were significantly higher than those in healthy controls group, and decreased after 1 month of anti-tubercular therapy." (PMID 35095520, 2021). "A five protein panel of complement factor H related 5, LRG1, C-reactive protein, lipopolysaccharide binding protein, and serum amyloid A1 had specific predictive power in distinguishing tuberculosis and other respiratory diseases." (PMID 35095520, 2021).
acute kidney injury (3 papers, 2011 to 2023). Sudden and sustained deterioration of the kidney function characterized by decreased glomerular filtration rate, increased serum creatinine or oliguria. "Interestingly, LRG1 is cleared in urine and its excretion rises in cases of renal failure and renal tubular injury." (PMID 37148275, 2023).
anemia (3 papers, 2021 to 2024). A reduction in the number of red blood cells, the amount of hemoglobin, and/or the volume of packed red blood cells. "This study aimed to examine the possible correlation between LRG1 and one of the most common diseases affecting children in developing countries, namely iron deficiency anemia." (PMID 37513518, 2023). "In this study, we investigated the association between LRG1 and several iron deficiency anemia markers, including hemoglobin (Hb), albumin, red cell distribution width (RDW), iron, ferritin, and Hb transferrin saturation." (PMID 37513518, 2023). "While LRG1 has been previously reported to be involved in several health conditions, we herein describe, for the first time, its involvement in iron deficiency anemia." (PMID 37513518, 2023). "Our data show that these various markers of anemia are significantly associated with LRG1, suggesting that LRG1 might be considered a potential iron deficiency marker." (PMID 37513518, 2023). "This indicates that the LRG1 upregulation observed in children diagnosed with anemia might be a consequence of iron deficiency anemia." (PMID 37513518, 2023). "Therefore, we plan to perform a longitudinal study to further explore the association between LRG1 and iron deficiency anemia." (PMID 37513518, 2023). "While the exact relationship between LRG1 and iron deficiency anemia remains largely unclear, one hypothesis is based on its involvement in the regulation of HIF-1α protein expression, because it has been shown that iron deficiency increases HIF-1α which regulates VEGF." (PMID 37513518, 2023). "Hence, the proposed mechanism suggests that iron deficiency anemia might indirectly regulate LRG1 expression, possibly by upregulating HIF-1α expression, which regulates direct targets of LRG1 promoter including IL-6 and TNFα." (PMID 37513518, 2023). "C-reactive protein (CRP) levels (P = 0.002), anemia (P = 0.037), hypercalcemia (P = 0.023), and grade (P = 0.031) were independent predictors of serum LRG1 levels in ccRCC." (PMID 38658967, 2024). "CRP, anemia, and hypercalcemia, all of which are related to inflammation and, tumor grade, are independent predictors of serum LRG1 levels." (PMID 38658967, 2024). "LRG1 served as a serum marker associated with inflammation, indicated by CRP, anemia, hypercalcemia, and malignant potential in ccRCC." (PMID 38658967, 2024). "Given that both LRG1 and iron deficiency regulate HIF-1α expression, it is vital to explore the association between LRG1 and anemia." (PMID 37513518, 2023). "LRG1 has also been negatively correlated with Hb levels in kidney transplant patients, possibly due to a secondary anemia induced by decreased renal function." (PMID 37513518, 2023). "While LRG1 has been shown to be associated with several health conditions, its association with iron deficiency anemia, especially in children, has not been previously explored." (PMID 37513518, 2023). "However, due to the cross-sectional nature of this study, it cannot be deduced whether increased LRG1 is involved in the pathogenesis of anemia or is the consequence of anemia." (PMID 37513518, 2023). "In addition, alpha-2-HS-glycoprotein and LRG1 were the most prospective candidates for different myelodysplastic syndrome subgroups, including refractory cytopenia with multilineage dysplasia, refractory anemia or refractory anemia with ringed sideroblasts, etc." (PMID 35095520, 2021). "Our data show that plasma LRG1 levels were increased in children diagnosed with anemia [31.1 (24.6, 43.2) μg/mL] compared to non-anemic children [29.2 (22.7–35.95) μg/mL] (p = 0.07)." (PMID 37513518, 2023). "Higher LRG1 levels were observed in children diagnosed with anemia [31.1 (24.6, 43.2) μg/mL] compared to non-anemic children [29.2 (22.7–35.95) μg/mL]." (PMID 37513518, 2023).
anemia (continued). "Nonetheless, it cannot be ruled out that the decreased anemia markers (hemoglobin and albumin) reported in this study might also have contributed to the upregulation of the inflammatory markers, leading to an increase in LRG1 levels." (PMID 37513518, 2023).
chronic pancreatitis (3 papers, 2018 to 2024). A chronic inflammatory process causing damage and fibrosis of the pancreatic parenchyma. "Plasma LRG1 had an AUC of 0.79 (95% CI 0.73 to 0.86) when patients with early stage PDAC were compared with healthy controls and AUC of 0.68 (95% CI 0.59 to 0.78) when compared with patients with chronic pancreatitis." (PMID 38123998, 2024).
colon adenoma (3 papers, 2017 to 2022). An adenoma that arises from the colon. "Aberrant expression of serum LRG1 was correlated with a number of colonic adenomas." (PMID 35371990, 2022). "Proteomic biomarkers screening between adenomatous polyps and CRC patients revealed LRG1 is one of the upregulated serum biomarkers, which made LRG1 a novel biomarker for CRC development and tumorigenesis from colon adenoma." (PMID 29029535, 2017).
infarction (3 papers, 2022 to 2025). A localised pathological necrosis of tissue resulting from obstruction of the blood supply usually by a thrombus, an embolus, or vascular torsion. "Research has found that lactylation modification at the H3K18 site promotes post-infarction cardiac repair and improves cardiac function by activating the transcriptional expression of repair genes such as leucine-rich alpha-2-glycoprotein 1 (LRG1) and VEGF-α." (PMID 40589733, 2025). "Consistent with the hypothesis of LRG1 exerting some beneficial functions in tissue healing, it is reasonable to speculate that LRG1 might be part of these adaptive metabolic responses which ultimately support cardiomyocyte survival after infarction." (PMID 35062948, 2022).
juvenile idiopathic arthritis (3 papers, 2021 to 2025). Juvenile idiopathic arthritis (JIA) is the term used to describe a group of inflammatory articular disorders of unknown cause that begin before the age of 16 and last over 6 weeks. "During the treatment of interleukin-6 receptor blockers, serum levels of LRG1 has good prediction ability for systemic juvenile idiopathic arthritis." (PMID 35095520, 2021). "Serum LRG1 levels were normalized in the inactive systemic juvenile idiopathic arthritis phase after treatment." (PMID 35095520, 2021).
liver cancer (3 papers, 2017 to 2024). An epithelial or non-epithelial malignant neoplasm that arises from the liver. "Searching LRG1 expression in scRNASeqDB confirmed similar expression in single cells, with the highest expression rank (top 4% rank) observed in liver cancer cells." (PMID 29206167, 2017). "However, it has also been reported that the expression of LRG1 in liver cancer cell lines is lower than that in normal liver cells, and the overexpression of LRG1 could suppress the invasion and migration of liver cancer cells." (PMID 32047555, 2020).
malaria (3 papers, 2017 to 2022). Malaria is a serious and sometimes fatal disease caused by a parasite that commonly infects a certain type of mosquito which feeds on humans. "Differential abundance of LRG1 and CP was observed between dengue and malaria using MRM assays as well as in TMT-based quantitation." (PMID 33204009, 2020). "LRG1 is a recently identified biomarker able to distinguish between malaria and dengue infection." (PMID 35443155, 2022).
metastatic disease (3 papers, 2021 to 2024). "Using the innovative multiplex platform of Olink, we could establish the relationship between 92 immune-oncology-related proteins, levels of LRG1, and metastatic disease outcome." (PMID 38386171, 2024). "Furthermore, western blot (WB) and immunohistochemistry (IHC) analysis of tissues from primary and metastatic tumors also verified the upregulation of LRG1 in the liver metastatic lesions." (PMID 34930899, 2021).
multiple myeloma (3 papers, 2020 to 2025). "Flow cytometry, Western blot, proteome analysis, co-immunoprecipitation, immunofluorescence staining, and NOD/SCID mouse subcutaneous transplantation model were performed to investigate the role of exosomal LRG1 on multiple myeloma cell growth." (PMID 38871685, 2024). "Likewise, exosomes from platelets in patients with multiple myeloma presented elevated levels of leucine-rich alpha-2-glycoprotein 1 (LRG1), which interacts with Olfactomedin 4 (OLFM4) in tumor cells, activating the EMT signaling pathway." (PMID 39934930, 2025).
osteoarthritis (3 papers, 2017 to 2024). A noninflammatory degenerative joint disease occurring chiefly in older persons, characterized by degeneration of the articular cartilage, hypertrophy of bone at the margins and changes in the synovial membrane. "In osteoarthritis, LRG1 expression was found to be upregulated in articular cartilage and subchondral bone." (PMID 38667022, 2024). "LRG1 contributes to angiogenesis-coupled de novo bone formation by increasing angiogenesis and recruiting MSCs in the subchondral bone of osteoarthritis joints." (PMID 28358372, 2017). "Further studies were focused on the role of LRG1 in osteoarthritis." (PMID 28358372, 2017). "In osteoarthritis, tumor necrosis factor-α (TNF-α) induced LRG-1 expression in the subchondral bone and articular cartilage, and LRG-1 contributed to angiogenesis-coupled de novo bone formation in the subchondral bone of osteoarthritis joints." (PMID 30760292, 2019). "Notably, inhibition of TNF-α and LRG1 activity by Lenalidomide, an inhibitor of TNF-α production, in ACLT mice attenuated degeneration of osteoarthritis articular cartilage." (PMID 28358372, 2017).